RNU5E-8P (RNA, U5E small nuclear 8, pseudogene)
Gene: Small nuclear RNA gene on chromosome 3 (116,965,112 to 116,965,227, reverse strand). Ensembl gene ENSG00000200372.
Homologues: Orthologues: chimpanzee U5 (98% identical). Paralogues in human: RNU5E-10P (82% identical), RNU5E-4P (78% identical), RNU5E-6P (78% identical), RNU5E-7P (77% identical), RNU5A-4P (74% identical), RNU5B-4P (74% identical), RNU5A-6P (73% identical), RNU5F-3P (73% identical), RNU5F-7P (73% identical), RNU5A-3P (72% identical), RNU5E-5P (72% identical), RNU5E-9P (72% identical), and 13 more.